TPO (thyroid peroxidase)
Diseases named in the same sentence as TPO in open-access papers (continued):
Sharing a sentence is not in itself a finding about the gene and the disease.
Thrombocytopenia (continued). "The previous meta-analysis demonstrates that TPO-RAs are tolerable and can reduce grade 3 or 4 thrombocytopenia in solid tumors with CIT." (PMID 41403445, 2025). "Other areas needing exploration include NOAC-induced thrombocytopenia, long-term safety of thrombopoietin receptor agonists (TPO-RAs), and the impact of comorbidities like liver cirrhosis." (PMID 39263408, 2024). "In case of persistently severe thrombocytopenia within 14 days of TPO-RA, switching to TPO-RA is recommended." (PMID 38665297, 2024). "In recent studies, thrombopoietin receptor agonists (TPO-RA) for treating post-HSCT thrombocytopenia indicated efficiency and safety." (PMID 36873638, 2023). "In comparison with the control group, the incidence of grade 3 or 4 thrombocytopenia in the experimental group was lower, suggesting that TPO-RAs helped prevent the occurrence of severe thrombocytopenia." (PMID 38041150, 2023). "For primary outcomes, TPO-RAs significantly reduced the incidence of grade 3 or 4 thrombocytopenia (RR = 0.69, 95% CI: 0.52–0.91)." (PMID 38041150, 2023). "We report a case series of 6 individuals with breast cancer that experienced dose-reductions and therapy delays due to thrombocytopenia secondary to trastuzumab emtansine or trastuzumab deruxtecan therapy and received intervention with TPO-RA." (PMID 37335880, 2023). "Transplantation of donor-derived CD34+-selected stem cell boost and pharmacological therapy with TPO-RA are under investigation as other options for managing prolonged thrombocytopenia and PGF after alloHCT." (PMID 36817464, 2023). "TPO-RAs was suggested as an effective option to transfusions of platelets in the treatment of CLD with thrombocytopenia in the United States." (PMID 36258065, 2023). "Avatrombopag, a relatively new TPO-RA, has been approved for the treatment of thrombocytopenia in adults with chronic liver disease by the U.S. FDA." (PMID 36873638, 2023). "Although TPO-RA has shown limited efficacy to alleviate thrombocytopenia induced by conventional chemotherapy, they seem to be efficacious in the setting of HER2-targeted ADC therapy based on our small series." (PMID 37335880, 2023). "There was a lower incidence of grade 3 or 4 thrombocytopenia in patients receiving TPO-RAs (33.49%) compared to those receiving a placebo (48.78%) in both chemotherapy groups (RR = 0.69, 95% CI:0.52–0.91, P < 0.05)." (PMID 38041150, 2023). "In summary, this meta-analysis demonstrates that TPO-RAs are tolerable and can reduce grade 3 or 4 thrombocytopenia in solid tumors with CIT." (PMID 38041150, 2023). "The improved effect of post-HSCT thrombocytopenia in adults was found in the administration of avatrombopag which was a new TPO-RA." (PMID 36873638, 2023). "Recent studies showing the experience of TPO-RAs for thrombocytopenia after allo-SCT, support their safety and efficacy in this new setting, with a low number of side effects." (PMID 35268455, 2022). "Some reports have shown a complete remission of thrombocytopenia achieved by single-agent TPO-RA treatment." (PMID 34572358, 2021). "Platelet transfusion remains the cornerstone of managing thrombocytopenia in cancer, while we eagerly await the results of ongoing studies on antifibrinolytics and TPO-RAs." (PMID 33799591, 2021). "Before implantation, recombinant human thrombopoietin (rh-TPO) was usually given to the patients with thrombocytopenia until the peripheral platelet count reached beyond 50 × 109/L." (PMID 32158688, 2020). "Eltrombopag, which is an FDA-approved thrombopoietin-receptor agonist (TPO-RA) that is currently being evaluated as a treatment for chemotherapy-induced thrombocytopenia, was a top hit in the screen." (PMID 33256675, 2020). "Recent studies have also reported radiofrequency ablation (RFA) or tissue biopsy as perioperative management for thrombocytopenia using TPO-RA." (PMID 30969381, 2019).
Thrombocytopenia (continued). "Recently, TPO-RA has been used for the management of chemotherapy-induced thrombocytopenia and before radiofrequency ablation (RFA)." (PMID 30969381, 2019). "Our results suggest that the use of TPO or TPO mimetics to rescue MDM2 antagonist-mediated thrombocytopenia would be difficult." (PMID 26959882, 2016). "There are two additional case reports describing the use of TPO-RAs to treat refractory thrombocytopenia perisplenectomy." (PMID 27812394, 2016). "Sixteen patients (40%) showed persisting thrombocytopenia, fourteen of these in a range from 100–150 × 103/μL, one patient required thrombocyte transfusions until last follow-up and one was diagnosed with immune thrombocytopenia and received TPO-agonists." (PMID 36765625, 2023). "The high level of serine may be indicative of myeloma-related thrombocytopenia and may open avenues for potential dietary and therapeutic interventions such as serine-restrictive diets and TPO application for MM patients." (PMID 37055385, 2023). "Furthermore, eltrombopag and romiplostim as TPO-RA have been widely investigated in thrombocytopenia post-transplant and indicated well-tolerance and efficiency." (PMID 36873638, 2023). "For example, in patients at high risk, prophylactic medication of recombinant human thrombopoietin (rh-TPO) or thrombopoietin receptor agonists (TPO-RA) might be administered to prevent severe thrombocytopenia and to maintain chemotherapy dose intensity." (PMID 37849829, 2023). "After discovering the decrease of platelets induced by excessive serine in the BM microenvironment of MM, we asked whether thrombocytopenia could be improved by the administration of TPO, a critical regulator of megakaryopoiesis and thrombopoiesis." (PMID 37055385, 2023). "Thrombopoietin receptor agonists (TPO-RAs), Eltrombopag and Romiplostim, were approved in 2008 as a second line therapy for refractory ITP and few studies have reported their efficacy in immune cytopenias, such as SLE-associated thrombocytopenia." (PMID 34572358, 2021). "TPO-RAs have been studied for two major implications in cancer related thrombocytopenia." (PMID 33799591, 2021). "We found that eltrombopag, an FDA-approved thrombopoietin-receptor agonist (TPO-RA) that is currently being evaluated as a treatment for chemotherapy-induced thrombocytopenia, inhibits the growth of Ewing sarcoma cell lines in vitro in proliferation and colony formation assays." (PMID 33256675, 2020). "The application of TPO-RA may help alleviate thrombocytopenia in infants." (PMID 40041460, 2025). "Currently, TPO-RAs have been FDA-approved for immune thrombocytopenia in cases of insufficient response to pretreatment, periprocedural thrombocytopenia in patients with chronic liver disease, aplastic anemia, and thrombocytopenia associated with antiviral treatment of hepatitis C." (PMID 38041150, 2023). "In patients with symptomatic thrombocytopenia, we may consider TPO-RAs, azacitidine, or androgens." (PMID 36517487, 2022). "All patients did have significant thrombocytopenias and neutropenias, including in both tandem HSCT procedures, but these resolved with TPO-RAs and G-CSF administration giving engraftment times comparable to “regular” autologous HSCTs." (PMID 40743665, 2025). "Even though TPO-RAs, especially eltrombopag, were broadly evaluated in post-HSCT thrombocytopenia, only a few studies focused on pediatric patients." (PMID 36873638, 2023). "In the light of significantly higher serum TPO level among CIT patients, medical treatment other than recombinant TPO and TPO receptor agonist may be needed to recover thrombocytopenia without causing possible thrombosis, myelofibrosis, and even thrombocytosis." (PMID 30174705, 2018). "What’s worse, some types of thrombocytopenia have no available drugs to use, which increases the urgency of discovering novel mechanisms independent of TPO involving platelet production." (PMID 41296464, 2025).
Thrombocytopenia (continued). "This is the first time that combined avatrombopag with other thrombopoietic agents has cooperative effect in vivo in the treatment of thrombocytopenia, which was consistent with the in vitro results that AKR-501 (avatrombopag) in combination with TPO had an additive effect on megakaryocytopoiesis." (PMID 36405248, 2022). "Current treatments (e.g., granulocyte colony-stimulating factor [G-CSF] for neutropenia, erythropoiesis-stimulating agents [ESAs] or transfusions for anemia, thrombopoietin receptor agonists [TPO-RAs] or transfusions for thrombocytopenia) only manage symptoms after CIM occurs and do not prevent it." (PMID 41199846, 2025). "In case of refractory thrombocytopenia despite IVIG, corticosteroids, TPO-RAs, and rituximab, the use of fostamatinib, which is a tyrosine kinase inhibitor recently approved in 2018 by the FDA for the treatment of chronic ITP unresponsive to previous therapies, might be considered." (PMID 38665297, 2024). "On the other hand, severe GVHD may lead to prolong thrombocytopenia and no response to TPO-RA, which was shown in our univariate data." (PMID 36873638, 2023). "With regards to the subgroup analysis on romiplostim, the lack of statistical significance (p > 0.05) between the platelet count increase in romiplostim and non-romiplostim TPO-RA may be attributed to the difference in starting thrombocytopenia grades/platelet count." (PMID 38155484, 2025). "At present, only rhTPO and rhIL-11 have been approved by the NMPA to treat cancer treatment-induced thrombocytopenia (CTIT) in mainland China, but many studies have confirmed the efficiency and safety of TPO-RA drugs in non-hematologic malignancies." (PMID 40703542, 2025).
type 1 diabetes (32 papers, 2007 to 2026). "The present study determined that there is an association between Type-I diabetes mellitus and elevated levels of anti-TPO and anti-TG antibodies in women." (PMID 40735558, 2025). "Laboratory evaluation comprised blood counts, metabolic parameters, thyroid function tests, thyroid autoantibodies (anti-TPO, anti-Tg), and type 1 diabetes-related autoantibodies (GAD, IA-2, ZnT8)." (PMID 42122033, 2026). "Prevalence of thyroid dysfunction according to the presence of TPO-Abs at type 1 diabetes onset, and predictive values for future thyroid dysfunction development in the overall cohort." (PMID 41255538, 2025). "In our previous report, we found that TPO-Abs at type 1 diabetes onset had high sensitivity and, particularly, a high negative predictive value for thyroid dysfunction within 10 years." (PMID 41255538, 2025). "Prevalence of thyroid dysfunction according to the presence of TPO-Abs at type 1 diabetes onset, and predictive values for future thyroid dysfunction development in adults-onset patients." (PMID 41255538, 2025). "At type 1 diabetes diagnosis, TPO-Abs positivity is highly prevalent in both youth (<18 years) and adults (≥18 years), supporting universal screening at onset." (PMID 41255538, 2025). "Prevalence of thyroid dysfunction according to the presence of TPO-Abs at type 1 diabetes onset, and predictive values for future thyroid dysfunction development in patients diagnosed before 18 years of age." (PMID 41255538, 2025). "A rational screening strategy for thyroid disease in asymptomatic patients with type 1 diabetes should include measurement of TPO-Abs and thyrotropin at diagnosis, followed by annual thyrotropin assessment in antibody-positive individuals." (PMID 41255538, 2025). "She developed primary hypothyroidism with elevated antibodies to thyroid peroxidase and thyroglobulin after 25 weeks of treatment, and developed primary adrenal insufficiency with adrenal crisis and fulminant type 1 diabetes with ketoacidosis after 45 weeks." (PMID 38707904, 2024). "Although subjects with positive TPO-Abs at type 1 diabetes onset were eight times more likely to develop thyroid dysfunction than negative ones, the diagnostic accuracy was very high among subjects diagnosed in adulthood but lower in those diagnosed before the age of 18." (PMID 41255538, 2025). "It is unclear how local autoantigens could contribute to tear autoantibodies to thyroid peroxidase (TPO), a tissue-restricted thyroid secretory protein important in generation of thyroglobulin or IA-2, an islet-specific autoantigen for type 1 diabetes." (PMID 39936155, 2024). "Islet cell autoantibodies, glutamate-decarboxylase (GAD) autoantibodies, and thyroid peroxidase antibodies were positive; stimulated c-peptide and insulin levels were low, indicating type 1 diabetes mellitus (T1D)." (PMID 40612706, 2025). "Current evidence for repeating thyroid screening in asymptomatic patients who were TPO-Abs negative at type 1 diabetes diagnosis derived mainly from pediatric studies." (PMID 41255538, 2025). "A role for anti-TPO antibodies has been previously suggested in autoimmune conditions of non-thyroid origin other than PV, including type I diabetes mellitus and RA." (PMID 29675021, 2018). "In a previous report, we demonstrated that thyroid peroxidase antibodies (TPO-Abs) measured at the onset of type 1 diabetes had high sensitivity and, particularly, high negative predictive value for the development of thyroid dysfunction over 10 years of follow-up." (PMID 41255538, 2025).
thyrotoxicosis (31 papers, 2005 to 2026). A hypermetabolic syndrome caused by the elevation of thyroid hormone levels in the serum. "The carriers of A-allele have milder thyrotoxicosis (i.e., lower levels of circulating thyroid hormones, low T3/T4 ratio, high level of TPO antibodies, and lower heart rate) that possibly facilitates achievement of remission in the subgroup of patients carrying A-allele." (PMID 23193417, 2012). "Laboratory tests that may help differentiate between the different causes of thyrotoxicosis include a radiolabelled technetium or iodide thyroid scan, and measurement of anti–thyroid peroxidase (TPO) antibodies, TSH receptor antibodies, and inflammatory markers." (PMID 16363909, 2005). "Investigations revealed subclinical thyrotoxicosis with elevated anti-thyroid peroxidase antibody (anti-TPO) and low fasting cortisol with high concurrent adrenocorticotropic hormone (ACTH)." (PMID 32455083, 2020). "Excess intake of iodine is evidenced by the increased incidence of hyperfunction of the thyroid gland (thyrotoxicosis) and the activation of autoimmune processes in the thyroid gland, while the concentration of autoantibodies against thyroid peroxidase and thyroglobulin rises." (PMID 40432435, 2025). "Another key mechanism is that, APC might have ameliorated the thyrotoxicosis by regulating the expression of TPO and TSHR proteins." (PMID 31439949, 2019). "Exogenous IFN-α may also influence switching to a Th2 pathway, which can result in the development of autoantibodies (e.g., anti-TPO, anti-TG) resulting in thyrotoxicosis, due to thyroid follicular rupture and release of stored thyroid hormones into the circulation." (PMID 27042364, 2016). "Although asymptomatic, follow-up testing revealed biochemical thyrotoxicosis (peak FT4 of 3.9 ng/dL and TSH of 0.01 mIU/mL), with anti-TPO and anti-TG Ab levels at 308 IU/mL and 147 IU/mL, respectively, and negative TBII and TSIG antibody levels." (PMID 27340576, 2016). "- Symptoms: palpitations, weight loss, anxiety.- Labs: ↑ FT3 (6.25 pg/mL), normal FT4, ↓ TSH (0.03 μIU/mL).- Postpartum thyrotoxicosis diagnosed.- Treated with Neo-Mercazole.- Anti-TPO and anti-Tg antibodies were not assessed due to cost." (PMID 41496136, 2026). "Laboratory results typically show a state of thyrotoxicosis, with negative TPO antibodies, as well as increased C-reactive protein (CRP) and erythrocyte sedimentation rate." (PMID 39967901, 2024). "Biochemical thyrotoxicosis without clinical symptoms developed after 4 months (peak FT4 of 2.4 ng/dL and TSH of 0.01 mIU/mL) with repeat anti-TPO and TG antibody levels at >1000 IU/mL and 147 IU/mL, respectively, and TBII and TSIG remaining negative." (PMID 27340576, 2016).
congenital hypothyroidism (30 papers, 2012 to 2025). A thyroid hormone deficiency present from birth. "Pathogenic variants in TPO cause a severe form of congenital hypothyroidism, characterized by the immediate release of accumulated radioiodide following sodium perchlorate administration (OMIM #606765)." (PMID 40918675, 2025). "The molecular diagnosis was of course unnecessary for the clinical diagnosis of congenital hypothyroidism but is important for genetic counseling, TPO deficiency being an autosomal recessive disorder." (PMID 40626246, 2024). "We aimed to detect mutations of the TPO gene in 12 Chilean patients with congenital hypothyroidism due to dyshormonogenesis (CHD) and to characterize these patients clinically and molecularly." (PMID 39064575, 2024). "Various studies have been published about the mutations associated with CHD—precisely due to mutations in the TPO gene—especially in countries where a neonatal screening program and follow-up of patients with congenital hypothyroidism are carried out." (PMID 39064575, 2024). "We report the case of a paediatric female patient affected by Bannayan-Riley-Ruvalcaba syndrome (BRRS) and congenital hypothyroidism (CH) with homozygous mutation of the TPO gene." (PMID 37361526, 2023). "The insight into the effect of nonsynonymous mutations on TPO dimer’s structural features and its biological function is crucial to reveal the severity of congenital hypothyroidism." (PMID 37699049, 2023). "Inactivating mutations in TPO gene were shown to cause the autosomal recessive trait congenital hypothyroidism in humans and dogs." (PMID 34209805, 2021). "Many patients with congenital hypothyroidism have problems related to synthesis or iodination of TG that are connected to TPO deficiency." (PMID 31366075, 2019). "We report a 26-year-old German-Thai male with congenital hypothyroidism caused by a compound heterozygous mutation in the thyroid peroxidase (TPO) gene." (PMID 26761947, 2016). "We report on a novel TPO gene mutation in a German-Thai patient who presented with congenital hypothyroidism and large multinodular goiter." (PMID 26761947, 2016). "Defects in the TPO gene are the cause of the majority of cases of thyroid dyshormonogenesis with permanent congenital hypothyroidism." (PMID 26761947, 2016). "In summary, we report on a novel TPO gene mutation in a German-Thai patient who presented with congenital hypothyroidism and a large multinodular goiter." (PMID 26761947, 2016). "Congenital hypothyroidism (CH) is the most common neonatal endocrine disorder, and mutations in the thyroid peroxidase (TPO) gene have been reported to cause the disease." (PMID 26777044, 2015). "Ob­jec­ti­ve: Congenital hypothyroidism (CH) is the most common neonatal endocrine disorder and mutations in the TPO gene have been reported to cause CH." (PMID 25241611, 2014). "The c.2268dup mutation in thyroid peroxidase (TPO) gene was reported to be a founder mutation in Taiwanese patients with dyshormonogenetic congenital hypothyroidism (CH)." (PMID 24745015, 2014). "In this study, 41 patients (15 male and 18 female) with dyshormonogenetic congenital hypothyroidism were evaluated for TPO gene mutation." (PMID 22919382, 2012). "As TPO homodimer catalyzes the iodination process in the biosynthesis of thyroid hormones, therefore, understanding the interactions and how they are affected by mutations are essential to investigate the severity of congenital hypothyroidism." (PMID 37699049, 2023). "Mutations in TPO have been found in patients with congenital hypothyroidism." (PMID 24586183, 2014). "A study in China examined 192 patients with congenital hypothyroidism; the prevalence of thyroid peroxidase (TPO) enzyme system gene defects was 1%." (PMID 39857886, 2025). "No genetic variant was found in any of these genes, but we were able to confirm the molecular basis for congenital hypothyroidism with the demonstration of two mutants in the TPO gene." (PMID 40626246, 2024).